DAXX (death domain associated protein)
Diseases named in the same sentence as DAXX in open-access papers (continued):
Sharing a sentence is not in itself a finding about the gene and the disease.
α-thalassemia (continued). "The objective of this study was to analyze the expression and clinical role of mitosis regulators α-thalassemia/mental retardation syndrome X-linked (ATRX) and death-domain-associated protein (DAXX) in metastatic high-grade serous carcinoma (HGSC)." (PMID 32533344, 2020). "Conversely, they appear to be mutually exclusive with mutations in α-thalassemia/mental retardation syndrome X-linked (ATRX) and Death Domain Associated Protein (DAXX), two telomere-binding proteins mutated in ALT." (PMID 32204305, 2020). "Somatic mutations in the α-thalassemia/mental retardation syndrome X-linked proteins (ATRX) and the death domain-associated protein (DAXX) chromatin remodeling complex are by far the most common mutations in ALT and are highly correlated with ALT development." (PMID 32039009, 2019). "Genetically, ALT positive cancers frequently harbor inactivating mutations in the gene loci of α-thalassemia/mental retardation syndrome X-linked (ATRX), Death domain associated protein (DAXX), and H3 histone family member 3A (H3F3A/H3.3)." (PMID 30214690, 2018). "DAXX has been found to be associated with multiple proteins involved in transcriptional repression, such as HDAC1, DNA methyltransferase 1 (DMNT1), and α-thalassaemia/mental retardation syndrome X-linked (ATRX)." (PMID 30336783, 2018). "Second, somatic inactivating mutations in ATRX (α thalassemia/mental retardation syndrome X-linked) and DAXX (death-domain associated protein) were detected in 18% and 25% of the cases, respectively." (PMID 28098761, 2017). "Furthermore, a majority of gliomas with histone mutations cluster with mutations in ATRX (α-thalassemia/mental retardation syndrome X-linked), DAXX (death-domain associated protein), and p533." (PMID 33931704, 2021). "Likewise, the chaperones alpha thalassemia/mental retardation syndrome X-linked chromatin remodeler (ATRX) and death domain-associated protein (DAXX) load histones onto telomeric and repetitive DNAs." (PMID 33109754, 2020). "Prior studies have related alterations in the alpha thalassemia/mental retardation syndrome X-linked (ATRX), death domain-associated protein (DAXX), or SWI/SNF related, matrix associated, actin dependent regulator of chromatin (SMARCAL1) genes with ALT in some cancers." (PMID 31462295, 2019).
Alpha-thalassemia (42 papers, 2012 to 2025). Alpha-thalassemia is an inherited hemoglobinopathy characterized by impaired synthesis of alpha-globin chains leading to a variable clinical picture depending on the number of affected alleles. "The most well-characterized mutations involve loss-of-function alterations in the Alpha Thalassemia/Mental Retardation Syndrome X-Linked (ATRX)/Death Domain-Associated Protein (DAXX) complex." (PMID 40723168, 2025). "Further mechanisms such as epigenetic changes within tumor cells and mutations in DAXX (death-domain-associated protein) or ATRX (alpha thalassemia/mental retardation syndrome X-linked) have also been proposed." (PMID 40384778, 2025). "Alpha-thalassemia/mental retardation syndrome X-linked (ATRX) is a chromatin-remodelling factor that exists in a complex with death domain-associated protein (DAXX) and is essential for incorporating Histone 3.3 (H3.3) into telomeres." (PMID 35326717, 2022). "Prior studies have linked alterations in the alpha thalassemia/mental retardation syndrome X-linked (ATRX) or death domain-associated protein (DAXX) genes with ALT in a subset of cancers." (PMID 35740680, 2022). "Alpha thalassemia/mental retardation syndrome X-linked (ATRX) interacts with death domain-associated protein (DAXX) and the histone H3.3 variant in heterochromatin remodeling and maintenance of telomere structure and function." (PMID 33106857, 2021). "Exon sequencing of paediatric HGGs identified recurrent somatic mutations (K27M, G34R/V) in histone H3 and inactivating mutations in the Death-domain associated protein/Alpha thalassemia-mental retardation (DAXX/ATRX) genes, leading to DNA hypomethylation." (PMID 32331249, 2020). "Characteristics of the sporadic form of PNETs are mainly gene mutations in DAXX (death-domain-associated protein) or ATRX (alpha thalassemia/mental retardation syndrome X-linked)." (PMID 33384663, 2020). "Note that these TSC2 gene mutations have not been detected as frequently as multiple endocrine neoplasia type 1 (MEN1) and death domain-associated protein/alpha thalassemia/mental retardation syndrome X-linked (DAXX/ATRX) gene mutations." (PMID 25889454, 2015). "The ATRX (alpha-thalassemia/mental retardation syndrome X-linked) and DAXX (death-domain associated protein) genes are involved in the ATRX/DAXX pathway, which is frequently mutated in pNETs, particularly those that are well differentiated and advanced or metastatic." (PMID 40429384, 2025). "The four different residues in the core domain are critical for the recognition of H3.3 by dedicated protein chaperones: the histone cell cycle regulator (HIRA) and the death domain associated protein/alpha thalassemia/mental retardation syndrome X-linked (DAXX/ATRX) complexes." (PMID 33353064, 2020). "Loss of function or mutations on alpha thalassemia/mental retardation syndrome X-linked (ATRX) or death-domain associated protein (DAXX) genes leads to ALT activation and maintenance, and often associated with growth factor receptor gene amplification in cancers." (PMID 28740573, 2017). "Mutations in the alpha thalassemia/mental retardation X-linked (ATRX) and death domain-associated protein (DAXX) genes result in genomic instability." (PMID 39954168, 2025). "Among the numerous molecular biomarkers under investigation, the chromatin remodelling proteins DAXX (death-domain associated protein) and ATRX (alpha-thalassemia/intellectual disability syndrome X-linked) have gained increasing attention." (PMID 41472189, 2025). "The alpha thalassemia/mental retardation syndrome X-linked (ATRX) gene and its partner, death associated protein 6 (DAXX) gene, encode proteins which incorporate the histone variant H3.3 into telomeric pericentric chromatin." (PMID 37958407, 2023).
Alpha-thalassemia (continued). "Whole exome sequencing of pNET has recently demonstrated that about 43% of pNETs have somatic mutations in the genes ATRX (alpha-thalassemia/mental retardation syndrome X-linked) and/or DAXX (death domain associated protein)." (PMID 36835048, 2023). "Through the chaperones ATRX (alpha thalassemia/mental retardation syndrome X-linked) and DAXX (Fas death domain-associated protein), H3.3 is deposited at repetitive regions such as telomeres and centromeres, serving genome stabilization functions." (PMID 25675407, 2015). "Additionally, targeting alpha thalassemia/mental retardation syndrome X-linked chromatin remodeler (ATRX) and death domain-associated protein (DAXX), which load histone 3.3, with CRISPR stimulated BZLF1 and BMRF1 expression." (PMID 34572593, 2021). "Alpha thalassemia/mental retardation syndrome X-linked chromatin remodeler (ATRX), a DAXX (death domain-associated protein) interacting protein, is often lost in cells using the alternative lengthening of telomeres (ALT) pathway, but it is not known how ATRX loss leads to ALT." (PMID 31895940, 2020). "Finally, inactivation of one or both of the ATP-dependent chromatin remodelers Alpha-Thalassemia/mental Retardation X-linked (ATRX) and Death domain-Associated protein-6 (DAXX) are often found in ALT tumors." (PMID 31552268, 2019). "Several ND10 constituent proteins, including PML (promyelocytic leukemia), Sp100 (speckled protein of 100 kDa), hDaxx (human death domain-associated protein 6), and ATRX (alpha thalassemia/mental retardation syndrome X-linked) can limit the replication of an ICP0 null HSV-1 mutant." (PMID 24852129, 2014). "Loss of immunostaining for alpha-thalassemia/mental retardation X-linked (ATRX) and Death Domain Associated Protein (DAXX, pancreatic NET) correlates with loss of function mutations and is associated with well-differentiated disease and may have prognostic value [34, 39••]." (PMID 36826704, 2023). "On the contrary, several gene mutations may characterize well-differentiated NETs, as observed with Menin 1 (MEN1), Death Domain Associated Protein (DAXX), and alpha-thalassemia/mental retardation, X-linked (ATRX) mutations in well-differentiated pancreatic NETs." (PMID 35186729, 2022). "In addition, either the presence of MEN-1 (Multiple Endocrine Neoplasia-type 1) mutations, or mutations of DAXX (death-domain-associated protein) or ATRX (alpha thalassemia/mental retardation syndrome X-linked), did not improve OS with everolimus treatment (p = 0.34)." (PMID 35267558, 2022).
glioblastoma (15 papers, 2012 to 2024). The most malignant astrocytic tumor (WHO grade IV). "The observation that ATRX/DAXX mediates recruitment of H3.3 to telomeres is consistent with the finding that mutations in H3.3 may also be associated with ALT in pediatric glioblastomas, which suggests that ATRX, DAXX, and H3.3 act in the same pathway to repress ALT." (PMID 23185534, 2012).
mental retardation syndrome X-linked (15 papers, 2014 to 2025). "For example, common somatic mutations in PanNET include MEN1 (multiple endocrine neoplasia type 1), DAXX (death-domain-associated protein)/ATRX (alpha alassemia/mental retardation syndrome X-linked), and mTOR (mammalian target of rapamycin) pathway genes." (PMID 33101770, 2020).
prostate carcinoma (15 papers, 2015 to 2025). A carcinoma that arises from epithelial cells of the prostate gland. "In prostate cancer, strong DAXX expression was associated strongly with a high Gleason grade, advanced pT stage, increased cell proliferation index, and early prostate-specific antigen recurrence." (PMID 31850367, 2019). "Death domain-associated protein (Daxx) has been recently implicated as a positive factor in ovarian cancer and prostate cancer, but the role of Daxx in oral squamous cell carcinoma (OSCC) has never been addressed." (PMID 26205068, 2016). "ChIPsequencing analyses showed in a prostate cancer cell model that the co-repressor DAXX (death domain associated protein) colocalized with DNMT1 near the TSS (transcriptional start site) of several ATG-related genes including ULK1 and DAPK3 (death-associated protein kinase 3)." (PMID 31861179, 2019). "In addition, DAXX may function as a novel anaphase-promoting complex or cyclosome inhibitor and promote chromosome-instability cancer predisposition during prostate cancer development." (PMID 31850367, 2019). "In human prostate carcinomas, strong DAXX protein expression has been shown to correlate with higher malignancy (e.g., higher Gleason grades) and increased tumour cell proliferation." (PMID 41472189, 2025). "In the HCT116 colon cancer xenograft model (both female and male mice) and a prostate cancer xenograft model (male mice), similar tumor growth phenotypes were observed: DAXX depletion slowed, while WT DAXX OE accelerated, tumor growth." (PMID 37045819, 2023). "For example, in leukemias and prostate cancer, promyelocytic leukemia (PML) plays a critical regulatory role by inhibiting HAUSP activity through death domain-associated protein (DAXX), which in turn favors PTEN nuclear localization." (PMID 36385557, 2022). "For example, DAXX is overexpressed in many types of cancer such as prostate cancer, ovarian cancer, gastric cancer, and gliomas." (PMID 35087762, 2021). "Work in HeLa cells additionally suggests that overexpressed CENPA is directed to gene regulatory elements through interaction with DAXX, a protein that has been previously been shown to be overexpressed in prostate cancer." (PMID 32371391, 2020). "Given DAXX's putative regulatory role in autophagy, future studies may consider DAXX as a candidate marker and therapeutic target for prostate cancer." (PMID 26097870, 2015). "Furthermore, ONCOMINE meta-analysis revealed that overexpression of DAXX is common in prostate cancer patients and correlates with lower survival rates, suggesting that, in certain cases, DAXX may present itself as a viable therapeutic target." (PMID 29479426, 2018). "One study suggests that DAXX binds to anaphase promoting complex (APC) coactivators Cdc20 and Cdh1 to inhibit the degradation of APC, thereby promoting chromosome instability during prostate cancer development." (PMID 35087762, 2021). "It is thus conceivable that either HJURP or DAXX carries out a chaperone like function for CENPA in prostate cancer, although re-ChIP assays involving CENPA and HJURP together or CENPA and DAXX together would be necessary to prove the presence of such a mechanism." (PMID 32371391, 2020). "Moreover, prostate carcinomas showed increased expression of DAXX compared with non-malignant tissues." (PMID 41472189, 2025). "In earlier studies, using the same large prostate cancer cohort we had described other very strong and often independent prognostic features such as for example ß3-tubulin, CD57, DAXX, HOXB13, KPNA2, RBM3, mTOR, p62, and TYMS, that might also be worth testing in multiparametric prognostic kits." (PMID 28415558, 2017). "This pilot study aimed to investigate the expression of DAXX and ATRX in urothelial and prostate carcinomas, as well as in non-neoplastic tissues." (PMID 41472189, 2025).
ovarian carcinoma (14 papers, 2018 to 2023). A malignant neoplasm originating from the surface ovarian epithelium. "A previous study of ours demonstrated that the death-associated protein 6 (DAXX) could induce ovarian cancer ascites formation by activating the ERK signaling pathway." (PMID 32711570, 2020). "DAXX overexpression enhanced the proliferation, colony formation, and migration of ovarian cancer cells." (PMID 36875159, 2023). "In ovarian cancer cells, DAXX interacts with promyelocytic leukemia protein and is localized to nuclear bodies PML in the subnuclear domain." (PMID 36875159, 2023). "Overexpression of DAXX promoted ovarian cancer cell proliferation, colony formation, and migration, whereas DAXX depletion by RNA interference had the opposite effects." (PMID 35087762, 2021). "DAXX expression was additionally studied in 15 cancer cell lines, including 4 ovarian carcinoma lines, and in 81 of the 400 HGSC effusions using Western blotting." (PMID 32533344, 2020). "The substrates of CN, including c-Jun, DAXX, BAD, Rb and Drp1, were associated with the prognosis in ovarian cancer." (PMID 31399054, 2019). "In our previous study, we found that DAXX co-localized with PML in ovarian cancer cells and mouse ovarian surface epithelium (mOSE)." (PMID 30336783, 2018). "In our previous study, we found that DAXX was significantly expressed in human ovarian cancer tissue and weakly expressed in normal ovarian tissue." (PMID 30336783, 2018). "In addition, DAXX is functional in ovarian cancer by activating the ERK signaling pathway and in breast cancer by impeding DNA damage repair." (PMID 36077718, 2022). "DAXX acts as an oncogene by interacting with PML to protect ovarian cancer cells from DNA damage." (PMID 35087762, 2021). "However, DAXX interacts with transcription regulators that regularly and directly stimulate proliferation in ovarian cancer cell line ES-2." (PMID 31614769, 2019). "We found that CEBP-β and DAXX were significantly expressed in human ovarian cancer tissues." (PMID 30336783, 2018). "Two genes (DAXX, ADAM17) are involved in ovarian cancer and three genes (TNFRSF1A, TIMP4, COL1A2) are exclusive to breast cancer." (PMID 31205821, 2019).
insulinomas (13 papers, 2017 to 2025). "With regards to the most common genes that mutate in pancreatic neuroendocrine neoplasms (panNENs) (MEN1, ATRX and DAXX) only loss of ATRX was detected in insulinoma sample." (PMID 34737724, 2021). "It was posited from these results that ATRX and DAXX mutations, which are typically more characteristic of NF-pNETs, may be more common in malignant insulinomas than in their less aggressive counterparts." (PMID 36835815, 2023). "YY1 was shown to be recurrently mutated in insulinomas, while mutations in ATRX/DAXX/MEN1 are very uncommon." (PMID 32512761, 2020). "A recent study reported that DAXX knockdown increased cell proliferation in a rat insulinoma cell line." (PMID 31614769, 2019). "Therefore, in this review, we summarize the literature addressing ATRX/DAXX mutations and ALT in functioning sporadic PanNETs with an emphasis on insulinoma." (PMID 39954168, 2025). "Taken together, these data show that ATRX and/or DAXX mutations and ALT are mostly absent in indolent insulinomas, while they occur frequently in aggressive insulinomas." (PMID 39954168, 2025). "In insulinomas, mutations in MEN1, ATRX and DAXX that are often mutated in all PNETs occur in no more than 10 percent: 3%, 8% and 3%, respectively." (PMID 34737724, 2021). "We determined protein expression of ARX and PDX1 together with ATRX, DAXX, ARID1A, and H3K36me3 by immunohistochemistry, as well as ALT and CDKN2A deletions by fluorescence in situ hybridization (FISH), in a cohort of clinically defined sporadic insulinomas." (PMID 32103422, 2020). "Rarely, metastatic insulinomas show ARX positivity with concurrent loss of DAXX/ATRX and ALT activation, suggesting a distinct tumorigenic mechanism in malignant insulinomas similar to nonfunctional pancreatic NETs through transdifferentiation from α cell tumors." (PMID 40026252, 2025). "Therefore, it is not surprising to detect recurrent ATRX/DAXX mutations and ALT, which are factors known to correlate with worse prognosis and distant metastasis in functioning (insulinomas) as well as in non-functioning PanNETs." (PMID 39331358, 2024). "A recent large whole-genome sequencing study definitively established that insulinomas and non-functional PanNETs have distinct genetic underpinnings, and recurrent copy number variations together with ATRX and DAXX mutations are a characteristic feature of non-functional PanNETs." (PMID 32103422, 2020).